BRCA1 (BRCA1 DNA repair associated)
Diseases named in the same sentence as BRCA1 in open-access papers (continued):
Sharing a sentence is not in itself a finding about the gene and the disease.
triple-negative breast carcinoma (continued). "Furthermore, 70% of BRCA1-associated breast cancers are triple-negative breast cancer (TNBC): estrogen receptor (ER)-, progesterone receptor (PR)-, and HER2-negative cancers." (PMID 41283387, 2025). "MDA-MB-436, a triple negative breast cancer (TNBC) cell line with a natural BRCA1 mutation and the highest expression of TLK1 among the CCLE cell lines, exhibited significantly higher sensitivity to olaparib than MDA-MB-468, a BRCA1-proficient TNBC cell line, in a cell survival assay." (PMID 39844055, 2025). "However, only around 15–20% of triple-negative breast cancers (TNBC) are associated with a BRCA1 germline mutation." (PMID 39392573, 2025). "Hence, identifying HR-deficiencies by genomic analysis-for instance, BRCA1/2 used in triple-negative breast cancer-should be a part of the selection process for PARP inhibitor therapy." (PMID 38929955, 2024). "Notably, germline BRCA1/2 mutations are linked to distinct clinical features, including an increased risk of triple-negative breast cancer (TNBC) and a younger age of onset." (PMID 38910707, 2024). "This is exemplified by constitutional BRCA1 promoter methylation, and numerous studies have demonstrated that this epimutation is substantially associated with early-onset triple-negative breast cancer (TNBC) subtypes and high-grade serous ovarian cancer (HGSOC)." (PMID 38542081, 2024). "Similarly, PARP inhibitors have emerged as promising options for patients with BRCA1/2 mutations, especially in triple-negative breast cancers and rare subtypes like triple-negative apocrine carcinoma." (PMID 39685105, 2024). "Triple-negative breast cancer is strongly associated with the presence of BRCA1/2 mutations." (PMID 38539422, 2024). "Previous studies have shown BRCA1/2 mutations could predict sensitivity to platinum-based chemotherapy in triple-negative breast cancer (TNBC) tumors and ovarian cancer tumors." (PMID 36922847, 2023). "Furthermore, triple-negative breast cancer (TNBC) with BRCA1 mutations treated with ICB therapy was reported to improved clinical outcomes." (PMID 37350936, 2023). "Approximately 10% to 15% of triple-negative breast cancers (TNBC) have deleterious mutations in BRCA1 and BRCA2 and may benefit from PARP inhibitor treatment." (PMID 37773077, 2023). "BRCA1 pathogenic variants, high Ki67 score and young age were predictors of pathological complete response, while clinical nodal status predicted survival outcomes in triple-negative breast cancer." (PMID 36922883, 2023). "Moreover, 53BP1 deficiency was correlated with triple-negative breast cancer status and with BRCA1/2 mutations." (PMID 36553657, 2022). "In this retrospective observational study, we evaluated data from patients with triple-negative breast cancer (TNBC) treated with neoadjuvant chemotherapy (NACT) in order to better define the impact of germline BRCA1/2 (gBRCA1/2) mutation status on outcomes in this patient population." (PMID 36230495, 2022). "BRCA1 mutations have been linked to higher likelihood of triple negative breast cancer (TNBC)." (PMID 35406503, 2022). "MDA-MB-436, a triple-negative breast cancer cell line model harbouring a loss of function mutation in BRCA1, also exhibited EX527 and salermide sensitivity (BRCA1:c.5396+1G>A, SF50 = 18 μM and SF50 = 12 μM, respectively), suggesting that this effect was not private to SUM149 or DLD1 isogenic models." (PMID 34750509, 2021). "Moreover, the loss of ARH3 increased PARPi resistance in triple-negative breast cancer (TNBC) SUM149PT (BRCA1 mutant, BRCA2-WT) and SUM159PT (BRCA1/2-WT) cells." (PMID 34019811, 2021).
triple-negative breast carcinoma (continued). "Representatively, triple-negative breast cancer patients with germline or somatic pathogenic BRCA1/2 mutations are sensitive to cisplatin or carboplatin, which are recommended as the preferred regiments for HER2-negative breast cancer patients, as per the NCCN Guideline Version 1.2019." (PMID 32300589, 2020). "Together with the compelling proliferative effects of BRCA1 c.3257del revealed in the current study, we considered this pathogenic variant might especially contribute to the development of triple-negative breast cancer." (PMID 32879886, 2020). "BRCA1 mutation carriers have higher chances of developing triple-negative breast cancer (TNBC)." (PMID 32591500, 2020). "CST shows prominent features of BRCA1-mutated triple-negative breast cancers including increased motility, high proliferation rate, genome instability and sensitivity to platinum chemotherapy and PARP inhibitors (olaparib, veliparib, rucaparib and talazoparib)." (PMID 32053991, 2020). "Moreover, according to different epidemic molecular studies, BRCA1 mutation carriers have more chances of developing triple negative breast cancer subtype." (PMID 32778078, 2020). "Similarly, PARP inhibition triggered STING-dependent anti-tumor immunity in BRCA1-deficient ovarian cancer tumor models and in models of triple-negative breast cancer." (PMID 32076484, 2020). "Moreover, BRCA1 promoter hypermethylation are associated with early onset, poor histological differentiation and triple negative breast cancer." (PMID 32856871, 2020). "Our findings also provided suggestive evidence that BRCA1 c.3257del could cause a decline in BRCA1 mRNA/protein expression and promote cell proliferation, especially in triple-negative breast cancer." (PMID 32879886, 2020). "Furthermore, aggressive triple-negative breast cancer (TNBC) has also been associated with sporadic mutations in BRCA1." (PMID 30975222, 2019). "This might be especially relevant in the context of BRCA1-mutated triple-negative breast cancer cells." (PMID 31315653, 2019). "Interestingly, clinicopathological features associated with BRCA1-deficiency such as younger age at diagnosis, high-grade tumour, triple-negative breast cancer and basal-like subtype were similarly associated with increased T cell-inflamed signature." (PMID 31022191, 2019). "Moreover, in 12 patients with early onset triple negative breast cancer (age ≤ 40), 6 patients (50.0%) reported deleterious mutations in BRCA1/2." (PMID 29409476, 2018). "For example, miR-638 regulates cell differentiation and proliferation by targeting cyclin-dependent kinase 2 (CDK-2) in leukemic cells; and in BRCA1-deficient triple negative breast cancer tumors, miR-638 and miR-146 were suggested to perform as potential biomarkers for improved overall survival." (PMID 29263143, 2018). "We also compared a BRCA1-mutated, PARPi-sensitive triple negative breast cancer (TNBC) cell line, MDA-MB436, to a BRCA-proficient TNBC cell line, HCC114353, and observed PARPi-induced γH2AX in MDA-MB436 but not in HCC1143 cells, consistent with their PARPi-sensitivity status." (PMID 29992957, 2018). "Since germline mutations of BRCA1 often lead to breast tumors that are triple-negative breast cancer (TNBC) type, we aimed to investigate whether genetic deficiency in genes of the BRCA1-A complex is associated with risk to TNBC development." (PMID 26848770, 2016). "Women with triple-negative breast cancer have higher frequency of BRCA1/2 mutation as well." (PMID 26759753, 2016). "Targeted PARP1 inhibition has proven especially effective as a treatment for patients carrying a BRCA1 mutation, and in triple-negative breast cancer (because of the similarities with BRCA1-mutated tumors) leading to an inhibition of dual DNA repair pathways leading to cell death." (PMID 27357824, 2016).
triple-negative breast carcinoma (continued). "Similarly, triple-negative breast cancer (TNBC) patients were more likely to have BRCA1 mutations (P=0.001) and that these patients were diagnosed at a relatively younger age than non-TNBC patients (38 vs. 46 years, P=0.028)." (PMID 26221963, 2015). "Triple-negative breast cancers are often linked to inactivation of the BRCA1 tumor suppressor gene." (PMID 26392359, 2015). "BRCA1 mutation is associated with developing triple-negative breast cancer of the basal subtype." (PMID 25531315, 2015). "Triple negative breast cancer is an especially appealing malignancy for treatment with Chk1 inhibitors, since these cancers have faulty replication fork repair, either from inherited or acquired BRCA1/2 deficiencies." (PMID 25024738, 2014). "Interestingly, triple-negative breast cancer cells with mutated BRCA1 or with wild-type BRCA1 showed high sensitivity to oxidative DNA damage because of their genomic instability and defective DNA-repair system." (PMID 25229616, 2014). "Our finding suggests that BRCA1 promoter methylation may also have an etiological role on the development of triple-negative phenotype and underlie triple-negative breast cancer." (PMID 23405268, 2013). "BRCA1 mutations are associated with triple-negative breast cancer, which may contribute to the early age distribution of this subtype." (PMID 22452927, 2012). "Importantly, carriers of mutations in the breast cancer susceptibility gene 1, BRCA1, frequently have basal-like and/or triple-negative breast cancers." (PMID 23110154, 2012). "The purpose of this study was to examine the regulation of prosurvival factors heat shock factor 1 (HSF1) and breast cancer susceptibility gene 1 (BRCA1) by a natural withanolide withaferin A (WA) in triple negative breast cancer cell lines MDA-MB-231 and BT20." (PMID 25969759, 2012). "We investigated a hospital-based series of 40 consecutive patients with triple-negative breast cancer for mutations in the whole coding sequences of BRCA1 and BRCA2 as well as in the two genes PALB2 and BRD7, which encode interaction partners of the BRCA1 protein." (PMID 23110154, 2012). "Recently, it was suggested that screening women with early-onset triple-negative breast cancer (TNBC) may be a cost-effective method with which to identify BRCA1 mutation carriers in Caucasian women." (PMID 23116406, 2012). "Genetic mutations such as BRCA1 convey dramatically increased risks of triple-negative breast cancer, and the results of genome-wide association studies may eventually guide even more personalized risk prediction." (PMID 21092082, 2010). "There are some promising data that platinum-based chemotherapy may be more effective in patients with BRCA-1 germline mutations or in "triple-negative" breast cancer." (PMID 20426817, 2010). "Interestingly, a study carried out on 237 triple-negative breast cancer (TNBC) cases indicated that the promoter hypermethylation of BRCA1 is more frequent than BRCA1 germline mutations, suggesting that both alterations can independently drive malignant breast tumorigenesis." (PMID 37761820, 2023). "For hormone-positive patients, inactivating NF1 mutations could be used as the prognostic biomarker of endocrine therapy resistance; for patients with triple-negative breast cancer, germline BRCA1/2 mutations could be employed to choose the appropriate medicine." (PMID 35494043, 2022).
triple-negative breast carcinoma (continued). "BET bromodomain inhibitors such as JQ1 are active against triple-negative breast cancer cell lines and xenografts; these aggressive cancers have poor prognosis and no targeted therapies and account for a high proportion of cancers arising in BRCA1 mutation carriers." (PMID 29921600, 2018). "However, EGFR missense mutations identified in the BRCA1/2 tumours were different from those encountered in our triple negative breast cancer study, possibly due to different patient selection where the BRCA1/2 linkage of our study cohort is unknown." (PMID 21457545, 2011). "Tumoral BRCA1 promoter methylation occurs frequently in triple-negative breast cancer (TNBC) and contributes to homologous recombination deficiency (HRD)." (PMID 41654537, 2026). "RTx-303 additionally enhanced olaparib activityin the BRCA1 mutant triple negative breast cancer(TNBC) MDA-MB-436cell derived xenograft model." (PMID 41124685, 2025). "In vivo efficacy was evaluated in xenograft models of triple-negative breast cancer (TNBC) and BRCA1/2-deficient tumors, including intracranial medulloblastoma." (PMID 41077566, 2025). "Most BRCA1 carriers develop triple-negative breast cancer (TNBC)—estrogen receptor (ER)-, progesterone receptor (PR)-, and HER2 -negative cancers—which originates from ER/PR/HER2-negative breast progenitor cells." (PMID 41283387, 2025). "Most triple-negative breast cancers (TNBC) are sporadic in nature and often associated with dysfunction of the BRCA1 or BRCA2 genes." (PMID 39392573, 2025). "Due to epigenetic changes in the breast cancer gene 1 (BRCA-1), triple-negative breast cancers (TNBC) are more responsive to platinum compounds." (PMID 40443638, 2025). "We generated hypomorphic BRCA1 and BRCA2 variants of the HRR proficient triple negative breast cancer cell line MDA-MB-231." (PMID 39819384, 2025). "Around 22% of BCs are estimated to exhibit a BRCA1/2 alteration, whereas a functional deficit in the HR system overseen by BRCA1 has been identified in 69% of triple-negative breast cancers (TNBCs)." (PMID 41011327, 2025). "We first assessed the response of 4T1, a murine BRCA1-proficient triple negative breast cancer cell line, in vitro by clonogenic survival assays." (PMID 39730675, 2024). "BRCA1-methylated triple negative breast cancer-derived xenografts that had been treated by neoadjuvant chemotherapy responded poorly to olaparib, similarly to wild-type BRCA1." (PMID 39769312, 2024). "In this case, the phenotype resembles a typical presentation of BRCA1-related cancer with triple-negative breast cancer at a young age of onset." (PMID 39021548, 2024). "Recent research has also shown that combining CPT-11 (the prodrug of SN-38) and PARPi achieved synergistic inhibition in both BRCA1 wild-type and BRCA1 mutant triple-negative breast cancer (TNBC) cell lines in vitro." (PMID 38178200, 2024). "Other studies have shown that luminal A has a prevalence of 49% in PIK3CA mutations, while BRCA1 and BRCA2 mutations are characteristic of triple negative breast cancer." (PMID 39264897, 2024). "The number of BRCA1/2 tests performed and the detection rates among newly diagnosed and follow-up patients, particularly focusing on triple-negative breast cancer (TNBC) cases, were analyzed." (PMID 38791944, 2024). "Restoration of the breast cancer 1 (BRCA 1) gene expressions in BRCA1-mutant triple-negative breast cancer cell lines can increase the expression of RHOB, resulting in reduced migration capacity." (PMID 39376611, 2024). "It was observed that a higher proportion of BRCA1 carriers had the triple-negative breast cancer subtype, whereas more BRCA2 carriers exhibited estrogen receptor (ER) + and progesterone receptor (PR) + subtypes." (PMID 38167124, 2024).
triple-negative breast carcinoma (continued). "In MDA-MB-231 triple-negative breast cancer cells, both compounds reduced BRCA1 levels while also increasing sensitivity to olaparib." (PMID 38993666, 2024). "Analyses of the Ku-DBi sensitivity were performed in the BRCA1 mutant triple-negative breast cancer (TNBC) cell line MDA-MB-436 and the BRCA1 wild-type MDA-MB-468." (PMID 39409907, 2024). "Neoadjuvant olaparib did not improve pCR rates, EFS or OS when added to carboplatin–paclitaxel and anthracycline-based chemotherapy in patients with triple-negative breast cancer who were germline BRCA1 and BRCA2 wild type." (PMID 38588696, 2024). "A study details the results of the PARTNER trial, a prospective, randomized controlled trial of the use of neoadjuvant olaparib with carboplatin–paclitaxel chemotherapy in patients with triple-negative breast cancer who were germline BRCA1 and BRCA2 wild type." (PMID 38588696, 2024). "In triple-negative breast cancer, quercetin can control the beta-catenin signal, leading to the reversion of epithelial-mesenchymal transition and the increase in BRCA1 expression." (PMID 39858410, 2024). "The other cohort (reported here) consisted of patients with triple-negative breast cancer (TNBC) who were germline BRCA1 and BRCA2 wild type (gBRCAwt))." (PMID 38588696, 2024). "Germline mutations in the BRCA1 and BRCA2 genes are reported in about 15–20% of all triple-negative breast cancers." (PMID 38785549, 2024). "Collectively, these results support the notion that overexpression of TRIM47 reduces BRCA1 expression and ultimately leading to Olaparib sensitive in triple-negative breast cancer." (PMID 36906594, 2023). "The study included 2478 of a triple-negative breast cancers (TNBCs) and 3493 high-grade serous ovarian cancers (HGSOCs) cases and controls without a germline pathogenic variant of BRCA1 and concluded that testing for BRCA1 epimutation in blood may have implications in cancer prediction." (PMID 37752189, 2023). "Taken together, these results indicate that TRIM47 conferred Olaparib sensitive of triple-negative breast cancer and BRCA1 inhibits TRIM47 overexpression induced Olaparib sensitive both in vitro and in vivo." (PMID 36906594, 2023). "About 15% of Triple-Negative-Breast-Cancer (TNBC) present silencing of the BRCA1 promoter methylation and are assumed to be Homologous Recombination Deficient (HRD)." (PMID 37007122, 2023). "For BRCA1 and PALB2, rare missense variants were associated with an increased risk of overall and triple-negative breast cancer, respectively." (PMID 37790698, 2023). "Consistently, western blot assay showed that TRIM47 was inversely correlated with the expression levels of BRCA1 (r = −0.857, P < 0.001) in 10 freshly collected clinical triple-negative breast cancer samples." (PMID 36906594, 2023). "Strikingly, we found that overexpression of BRCA1 significantly reverse the effect of TRIM47 on Olaparib sensitive in triple-negative breast cancer." (PMID 36906594, 2023). "Analysis of 39 human triple-negative breast cancer tissue specimens using IHC analysis showed that TRIM47 expression was inverse correlated with the expression levels of BRCA1 (P = 0.021)." (PMID 36906594, 2023). "This study sought to identify BRCA1 and BRCA 2 mutations among triple-negative breast cancer female patients in one of the major teaching and referral hospitals in Kenya, to inform an ongoing larger study on genetic mutation testing." (PMID 37719058, 2023). "The inverse correlation between TRIM47 expression and BRCA1 pathway was further determined in a gene set enrichment analysis (GSEA) of triple-negative breast cancer specimens." (PMID 36906594, 2023). "Low expression of BRCA1 signifies worse prognosis in patients with triple negative breast cancer, while its high expression effectively inhibits invasion and metastasis." (PMID 36973651, 2023).